TP53TG1 (TP53 target 1)
Synonyms: H_RG012D21.9; LINC00096; TP53LC12; NCRNA00096; P53TG1; P53TG1-D; TP53AP1
Gene: Long non-coding RNA gene on chromosome 7 (87,322,943 to 87,345,596, reverse strand). Ensembl gene ENSG00000182165.
Diseases named in the same sentence as TP53TG1 in open-access papers:
TP53TG1 is named in the same sentence as 25 diseases in open-access papers, as found by Europe PMC text mining. Sharing a sentence is not in itself a finding about the gene and the disease. The quoted sentences say what the papers report.
glioma (9 papers, 2018 to 2026). A benign or malignant brain and spinal cord tumor that arises from glial cells (astrocytes, oligodendrocytes, ependymal cells). "On the otherhand, TP53TG1 is shown to promote cell proliferation andmigration in glioma cells under glucose deprivation." (PMID 31223218, 2018). "TP53TG1 can also function as a sponge of miR-524 and exert an oncogenic role in glioma." (PMID 34564314, 2021). "For example, TP53TG1 has been found to serve as a tumor suppressor in human colorectal cancer, gastric cancer, and non-small cell lung cancer, whereas it functions as an oncogene in glioma and pancreatic ductal adenocarcinoma." (PMID 34564314, 2021). "Furthermore, the documented roles of TP53TG1 in glioma cell proliferation and response to chemotherapy in lung cancer provide experimental support for our in silico prediction of a role for TP53TG1 in the response of GBM cells to TMZ." (PMID 32927769, 2020). "The expression of TP53TG1 was significantly increased in human glioma tissues or cell lines." (PMID 32258156, 2020). "Subsequently, 10 autophagy‐associated lncRNAs with prognostic value (PCBP1‐AS1, TP53TG1, DHRS4‐AS1, ZNF674‐AS1, GABPB1‐AS1, DDX11‐AS1, SBF2‐AS1, MIR4453HG, MAPKAPK5‐AS1 and COX10‐AS1) were identified in glioma patients using multivariate Cox regression analyses." (PMID 30984540, 2019). "Studies have increasingly pointed out the role of TP53TG1 in the progression of various cancers, where its expression is altered in several tumors, including hepatocellular carcinoma, breast cancer, gastric cancer, non-small cell lung cancer, colorectal cancer, and glioma." (PMID 41801317, 2026). "Furthermore, TP53TG1 may promote glioma cell proliferation and migration through affecting glucose metabolism." (PMID 34564314, 2021). "The knockdown of TP53TG1 significantly inhibited the migration ability of U87 cells under treatment with various levels of glucose, whereas the overexpression of TP53TG1 enhanced the expression of IDH1 and reduced the expression of PKM2 in glioma cells." (PMID 31654067, 2019).
hepatocellular carcinoma (7 papers, 2021 to 2026). A malignant tumor that arises from hepatocytes. "In some other cancers, such as non-small cell lung cancer, hepatocellular carcinoma, gastrointestinal cancer, and cutaneous melanoma, TP53TG1 serves as a cancer suppressor." (PMID 36267418, 2022). "LncRNA TP53TG1 inhibits hepatocellular carcinoma growth and metastasis by affecting the PRDX4/β-catenin axis." (PMID 34408984, 2021). "lncRNA TP53TG1 suppressed the progression of hepatocellular carcinoma through interacting with PRDX4 to promote its ubiquitin-mediated degradation, leading to inactivation of the WNT/β-catenin pathway." (PMID 34244473, 2021). "Previous studies reported that the high expression of TP53TG1 inhibited cancer cell apoptosis in PDAC and breast cancer and promoted cancer cell apoptosis in non-small cell lung cancer, hepatocellular carcinoma, gastrointestinal cancer, and cutaneous melanoma." (PMID 36267418, 2022).
gastric cancer (6 papers, 2022 to 2026). A primary or metastatic malignant neoplasm involving the stomach. "LncRNA TP53TG1 was low expressed in gastric cancer, and TP53TG1 obstructed the cell cycle and process, which broaden the field of treatment for gastric cancer." (PMID 38627627, 2024). "One study reported that m6A modifications were highly abundant in lncRNA TP53TG1 and that m6A modification‐induced overexpression of lncRNA TP53TG1 inhibited gastric cancer growth." (PMID 39023191, 2024). "Consistently, we found that the expression of TP53TG1 is up-regulated in most cancers except in colorectal and gastric cancers, perhaps due to chemotherapy and DNA methylation." (PMID 36267418, 2022). "TP53TG1 expression in tumors was significantly up-regulated (p-value < 0.05) in 15 of the 24 cancer types and was significantly down-regulated only in two cancer types, including colorectal and gastric cancer." (PMID 36267418, 2022).
breast carcinoma (5 papers, 2021 to 2026). "We further selected five lncRNAs (DSCR8, TP53TG1, CBR3-AS1, LINC01006, HAGLROS) that were not previously reported to be related to the drug sensitivity of breast cancer and performed qRT-PCR to verify their expression levels." (PMID 33494806, 2021).
colon cancer (5 papers, 2018 to 2024). "A different study, however, showed that TP53TG1 is a tumor suppressor by inhibiting the activation of the PI3K/Akt pathway to enhance the sensitivity of colon cancer cells to PI3K inhibitor KU-55933 and AKT inhibitor perifosine." (PMID 36005829, 2022).
non-small cell lung carcinoma (5 papers, 2018 to 2026). A group of at least three distinct histological types of lung cancer, including non-small cell squamous cell carcinoma, adenocarcinoma, and large cell carcinoma. "TP53TG1 also improves the sensitivity of the anti-tumor drug cisplatin in non-small cell lung cancer by interacting with the miR-18a/PTEN axis." (PMID 34564314, 2021). "The present study estimated the usefulness of 14 lncRNAs (HAGLR, ADAMTS9-AS2, LINC00261, MCM3AP-AS1, TP53TG1, C14orf132, LINC00968, LINC00312, TP73-AS1, LOC344887, LINC00673, SOX2-OT, AFAP1-AS1, LOC730101) for early detection of non-small-cell lung cancer (NSCLC)." (PMID 35053601, 2022).
colorectal cancer (4 papers, 2021 to 2026). A primary or metastatic malignant neoplasm that affects the colon or rectum. "Of these nineteen lncRNAs, miR-215, FOXD2-AS1, SATB2-AS1, TP53TG1, LINC01224, CRNDE, and DPP10-AS1 have been implicated in colorectal cancer (CRC)." (PMID 38666928, 2024). "LINC00493 and TP53TG1 are enriched and co-released in extracellular vesicles from colorectal cancer cells." (PMID 38611028, 2024).
lung carcinoma (2 papers, 2020 to 2021). "Meanwhile, LncRNAs such as GAS5, TP53TG1, and AC078883.3 have been associated with cisplatin sensitivity through miR‐21/PTEN, miR‐18a/PTEN, and PTEN/AKT axis, respectively, in human lung carcinomas." (PMID 33433063, 2021).
pulmonary fibrosis (2 papers, 2022 to 2025). Chronic progressive interstitial lung disorder characterized by the replacement of the lung tissue by connective tissue, leading to progressive dyspnea, respiratory failure, or right heart failure. "In vivo assays identified that forced expression of TP53TG1 by adeno-associated virus 5 (AAV5) not only prevented BLM-induced experimental fibrosis but also reversed established lung fibrosis in the murine model." (PMID 35661695, 2022). "Here, we found that overexpressing TP53TG1 reduced BLM-induced experimental pulmonary fibrosis in mice although TP53TG1 was predicted up-regulated in IPF whole lung." (PMID 35661695, 2022). "Nevertheless, the biological function and detailed molecular mechanisms of TP53TG1 remain to be elucidated in pulmonary fibrosis." (PMID 35661695, 2022). "In response to therapeutic AAV5-TP53TG1, the lung tissues of mice showed less fibrotic area, lighter Collagen I and α-SMA staining, indicating that TP53TG1 is able to impede the progression of lung fibrosis." (PMID 35661695, 2022). "Collectively, these data demonstrate the anti-fibrotic role of TP53TG1 in pulmonary fibrosis through inhibiting MYH9 protein expression, which might be attributed to decreased myofibroblasts differentiation and ECM deposition." (PMID 35661695, 2022). "Additionally, TP53TG1 has been identified as interacting with Myh9, leading to the downregulation of its expression, inhibition of fibroblast activation, and mitigation of pulmonary fibrosis." (PMID 41389878, 2025). "TP53TG1 as a MYH9 inhibitor might be target for the control of pulmonary fibrosis." (PMID 35661695, 2022). "Since we have found the TP53TG1 expression in IPF patients, we next explored the potential roles of TP53TG1 in experimental lung fibrosis in mice." (PMID 35661695, 2022). "In this study, we found that restoration of TP53TG1 levels in fibroblasts reduced TGF-β1 induced fibrogenesis of human embryonic fibroblast cells and BLM-induced pulmonary fibrosis in experimental mice." (PMID 35661695, 2022). "Our results suggest that TP53TG1 attenuates TGF-β1 induced fibrogenesis in MRC-5 cells, and the prevention of experimental pulmonary fibrosis in mice may be due to this function." (PMID 35661695, 2022). "TP53TG1 as a novel MYH9 protein inhibitor to suppress fibroblast activation and pulmonary fibrosis." (PMID 35661695, 2022).
retinoblastoma (2 papers, 2022 to 2024). A malignant tumor that originates in the nuclear layer of the retina. "Prior literature has demonstrated an oncogenic role for TP53TG1 in pancreatic ductal adenocarcinoma, retinoblastoma, and nasopharyngeal carcinoma, and future work will be needed to validate the function of this lncRNA in mCRPC." (PMID 38396008, 2024). "In addition, it has been determined that TP53TG1 is an oncogenic lncRNA in nasopharyngeal carcinoma and retinoblastoma." (PMID 35661695, 2022).
asthma (1 paper, 2022). "The top five AUCs for DElncRNAs of the T2 asthma and healthy control groups included PCAT19 (AUC = 0.949), TP53TG1 (AUC = 0.876), SNHG16 (AUC = 0.852), LINC01133 (AUC = 0.844), and PP7080 (AUC = 0.827)." (PMID 35480331, 2022).
cervical cancer (1 paper, 2022). A primary or metastatic malignant neoplasm involving the cervix. "TP53TG1 has been reported to be cancer-promoting in cervical cancer, but prognosis analysis showed its cancer-inhibiting function." (PMID 36267418, 2022). "Our study highlights the essential role of lncRNA TP53TG1 in the development of cervical cancer and discusses new regulatory mechanisms." (PMID 36267418, 2022). "In this study, we investigated the role of TP53TG1 in cervical cancer and explored whether TP53TG1 could function in transcriptional or post-transcriptional regulations." (PMID 36267418, 2022). "We found that TP53TG1 overexpression significantly inhibited cell proliferation and induced apoptosis, demonstrating that TP53TG1 may be a novel anti-oncogenic factor in cervical cancer." (PMID 36267418, 2022). "Since bulk RNA-seq obtains the average gene expression of various cells, to know whether TP53TG1 is highly expressed in malignant cells or in other cell types, we downloaded and analyzed the single cell data of cervical cancer tissue and adjacent tissue, respectively." (PMID 36267418, 2022).
Crohn disease (1 paper, 2024). A gastrointestinal disorder characterized by chronic inflammation involving all layers of the intestinal wall, noncaseating granulomas affecting the intestinal wall and regional lymph nodes, and transmural fibrosis. "ZNF91 and TP53TG1 in Crohn’s disease are related to the regulation of PPAR, MAPK, and metabolic signaling pathways." (PMID 39791702, 2024).
ovarian carcinoma (1 paper, 2020). A malignant neoplasm originating from the surface ovarian epithelium. "By searching related literature and databases, about 30% lncRNAs have been verified to play roles in the regulation of proliferation, invasion, and migration of ovarian cancer cells, including ZFAS1, SNHG1, GAS5, EMX20S, GIHCG, TP53TG1, EPB41L4A-AS1, SNHG8, SNHG6, and HCP5." (PMID 33519912, 2020).
cancer (24 papers, 2017 to 2026). A tumor composed of atypical neoplastic, often pleomorphic cells that invade other tissues. "Pan-cancer analysis also shows that higher expression of TP53TG1 was associated with a better prognosis, indicating that TP53TG1 inhibits the progression of cancer." (PMID 36267418, 2022). "Orilnc1, KIMAT1, SLCO4A1-AS1, LINC01420, KRAS1P, YWHAE, PART1, MALAT1, PCAT-1, lncRNA-NUTF2P3-001 and TP53TG1 are long non-coding RNAs (lncRNAs) whose interactions with KRAS have been verified in the context of cancer." (PMID 35139853, 2022). "Pan-cancer analysis shows that higher TP53TG1 expression was positively correlated with a higher overall survival rate, which confirmed that TP53TG1 exhibits tumor suppressor-like feature in cancer patients." (PMID 36267418, 2022). "We found that TP53TG1 was highly expressed in cell types C0 (cancer cells), C2 (cancer cells), C6 (endothelial cells), C9 (cancer cells) and C13 (cancer cells)." (PMID 36267418, 2022). "TP53TG1 has been reported as having dual roles by exerting tumor-suppressive and oncogenic activities that vary depending on the cancer type." (PMID 34564314, 2021). "Nonetheless, there are also studies that demonstrate TP53TG1 role in promoting the development of other types of cancers such as pancreatic adenocarcinoma, glioma (under low glucose levels) and nasopharyngeal carcinoma." (PMID 34575588, 2021). "Among genes and ERVs that were within 5000 bp distance from each other, and both significantly differentially expressed in the same direction (concordant), we identified two genes that played a role in various cancer types, TP53TG1 and RP4." (PMID 34944967, 2021). "Consequently, TP53TG1 is posited as a significant biomarker for tumor prognosis and is anticipated to be a potentially effective target for cancer therapies." (PMID 41801317, 2026). "Their downstream targets are regulated by TP53TG1 and may influence cancer progression in cells or clinical samples." (PMID 36267418, 2022). "This prompted us to investigate how TP53TG1 regulates the DDR pathway in cancer cells, which could affect the sensitivity of chemotherapy drugs." (PMID 36267418, 2022). "More importantly, TP53TG1 siRNA enhanced the anti-cancer effects of sorafenib." (PMID 36005829, 2022). "Taken together, these results suggest that TP53TG1 may have a dual role in cancer development, with a predominant oncogenic function." (PMID 36267418, 2022). "Tumor protein 53 target gene 1 (TP53TG1) is a newly identified lncRNA in recent years, and several studies have shown that TP53TG1 may play oncogenic or anti-oncogenic roles in different cancers." (PMID 36267418, 2022). "Inspired by previous discoveries that TP53TG1 may play oncogenic or anti-oncogenic roles in different cancers, TP53TG1 expression was compared between tumor and normal tissues in 24 cancer types from TCGA." (PMID 36267418, 2022). "Previous studies have reported that TP53TG1 has a dual role in cancer." (PMID 36267418, 2022).
cancer (continued). "TP53TG1 has also shown tumor suppressor properties due to its ability to prevent the nuclear localization of the oncogenic YBX1 protein, which has been associated with cancer progression." (PMID 34575588, 2021). "In contrast, OTX2-AS1 was significantly enriched in the floor-plate cluster together with TP53TG1, implicated in carcinoma but not as yet associated with a neuronal phenotype." (PMID 33445654, 2021). "Tumor protein 53 target gene 1 (TP53TG1, GenBank Accession Number NM_007233), a long intergenic non-protein-coding RNA with 751 nt in length, was revealed to exert a tumor-suppressor feature in human cancer." (PMID 29588850, 2018). "Previous studies have shown that lncRNA TP53TG1 can not only inhibit the development of GC by regulating the stability of CIP2A3430, but also play a promoting role in cancer development." (PMID 37258567, 2023). "The experimentally induced upregulation of TP53TG1 modulated the miR-18a/PTEN axis and enhanced cisplatin sensitivity and apoptosis of cancer cells." (PMID 35053601, 2022). "Future studies into how TP53TG1 functions in a cell-type-specific manner will be critical to determine the contribution of TP53TG1 to the pathogenesis of HCC and other types of cancer." (PMID 34564314, 2021). "Thirty-one proteins remain after screening (protein name marked in red), in which YBX1 has been reported to interact with several oncogenic lncRNAs, including TP53TG1, HULC, HOXC-AS3, and lincNMR, thereby regulating cancer progression and oncogene expression." (PMID 34266873, 2021). "Hence, TP53TG1 therapies could act as an efficient anti-cancer drug." (PMID 34575588, 2021). "Among these novel lncRNAs, the lncRNAs TP53TG1 and ENSG000246263, were recently uncovered in a study using a machine-learning method to stratify cancer-related lncRNAs." (PMID 32927769, 2020). "In this mini-review, we summarized the recent understanding of the molecular mechanisms of PKM2-associated LncRNAs, including MAFG-AS1, HULC, FEZF1-AS1, LincRNA-p21, MEG3, HOXB-AS3, TP53TG1 and Linc-ROR in cancer metabolism." (PMID 31654067, 2019). "This comprehensive analysis identified a batch of core lncRNAs that exhibited strong associations and high regulatory potential across multiple cancers, including NEAT1, MALAT1, GAS5, TP53TG1, and LINC00941, many of which have been previously confirmed to be closely related to cancer progression." (PMID 41373831, 2025). "TP53TG1 binds to RNA-binding protein YBX1 to block its function and acts as an anti-cancer agent." (PMID 36267418, 2022).